FMO1 (flavin containing dimethylaniline monoxygenase 1)
Description:
Broad spectrum monooxygenase that catalyzes the oxygenation of a wide variety of nitrogen- and sulfur-containing compounds including xenobiotics. Catalyzes the S-oxygenation of hypotaurine to produce taurine, an organic osmolyte involved in cell volume regulation as well as a variety of cytoprotective and developmental processes. In vitro, catalyzes the N-oxygenation of trimethylamine (TMA) to produce trimethylamine N-oxide (TMAO) and could therefore participate to the detoxification of this compound that is generated by the action of gut microbiota from dietary precursors such as choline, choline containing compounds, betaine or L-carnitine (By similarity).
Tractability: Antibody: UniProt predicts a signal peptide or a membrane-spanning region. PROTAC: its protein half-life has been measured.
Target class: Enzyme; Oxidoreductase
Gene: Protein-coding gene on chromosome 1 (171,248,471 to 171,285,978, forward strand). Ensembl gene ENSG00000010932.
Subcellular location: Endoplasmic reticulum membrane
Pathways (Reactome):
Metabolism: Degradation of cysteine and homocysteine; FMO oxidises nucleophiles
Gene Ontology:
Molecular function: hypotaurine monooxygenase activity; monooxygenase activity; N,N-dimethylaniline monooxygenase activity; protein binding; trimethylamine monooxygenase activity; flavin adenine dinucleotide binding; NADP binding
Biological process: glutathione metabolic process; sulfur oxidation; taurine biosynthetic process; toxin metabolic process; sulfur amino acid catabolic process; response to lipopolysaccharide
Cellular component: endoplasmic reticulum lumen; endoplasmic reticulum membrane
Genetic constraint (gnomAD): Loss-of-function variants: 22 observed, 35.41 expected, observed/expected ratio (o/e) 0.62, 90% interval 0.44 to 0.89. The upper end of that interval is the gene's LOEUF score, 0.89, which puts it in group 3 of 6, group 1 being the genes least tolerant of losing a copy. Missense variants: 536 observed, 590.75 expected, observed/expected ratio (o/e) 0.91, 90% interval 0.84 to 0.97. Synonymous variants: 204 observed, 212.96 expected, observed/expected ratio (o/e) 0.96, 90% interval 0.85 to 1.08.
Homologues: Orthologues: chimpanzee FMO1 (99% identical), macaque FMO1 (98% identical), dog FMO1 (89% identical), mouse Fmo1 (83% identical), guinea pig FMO1 (83% identical), rat Fmo1 (82% identical), rabbit FMO1 (79% identical), pig FMO1 (77% identical), Caenorhabditis elegans fmo-1 (38% identical), Caenorhabditis elegans fmo-5 (38% identical), Caenorhabditis elegans fmo-3 (36% identical), Caenorhabditis elegans C01H6.4 (20% identical), and 1 more. Paralogues in human: FMO2 (57% identical), FMO3 (54% identical), FMO5 (51% identical), FMO4 (51% identical), FOXRED2 (20% identical).
Diseases named in the same sentence as FMO1 in open-access papers:
FMO1 is named in the same sentence as 17 diseases in open-access papers, as found by Europe PMC text mining. Sharing a sentence is not in itself a finding about the gene and the disease. The quoted sentences say what the papers report.
Autoimmunity (2 papers, 2021 to 2022). The occurrence of an immune reaction against the organism's own cells or tissues. "From our analysis of the fmo1 esd4 double mutant, which is deficient in NHP biosynthesis, we showed that NHP signaling is also required for the autoimmunity in esd4." (PMID 35693184, 2022).
amyotrophic lateral sclerosis (1 paper, 2024). Amyotrophic lateral sclerosis (ALS) is a neurodegenerative disease characterized by progressive muscular paralysis reflecting degeneration of motor neurons in the primary motor cortex, corticospinal tracts, brainstem and spinal cord. "FMO1 levels decrease in the spinal cord of patients with amyotrophic lateral sclerosis, but increase in the myocardial tissue of patients with atrial fibrillation." (PMID 39480513, 2024).
diabetes mellitus (1 paper, 2022). A metabolic disorder characterized by abnormally high blood sugar levels due to diminished production of insulin or insulin resistance/desensitization. "Several lines of evidence have also supported the role of the secondary genes FMO1 and ALOX1 having interaction with CYP3A4 and PTGS1 in diabetes mellitus." (PMID 36051390, 2022).
nicotine dependence (1 paper, 2017). Physical and psychological dependence on nicotine. "A number of common variants in FMO1 were identified to be significantly associated with nicotine dependence, and we noted that there was an ethnic‐specific pattern." (PMID 28413702, 2017). "(2011) has identified significant association between SNPs of FMO1 and nicotine dependence." (PMID 28413702, 2017). "Specifically, we focused on the two genomic segments including FMO1,FMO3, and pseudo gene FMO6P, and aimed to investigate the potential association between FMO genes and nicotine dependence." (PMID 28413702, 2017). "Specifically, we focused on the two genomic segments including FMO1, FMO3 (protein coding genes for FMO 1 and 3), and FMO6P (pseudo gene), and aimed to investigate the potential association between FMO genes and nicotine dependence." (PMID 28413702, 2017). "In summary, we tested the genetic effects of three FMOs genes (FMO1, FMO3, and FMO6P) on nicotine dependence by performing targeted sequencing on 2,852 nicotine‐dependent and nondependent smokers." (PMID 28413702, 2017).
steatosis (1 paper, 2024). Increased lipid within the cytoplasm of cells. "On the other hand, two genes (CYP1A2 and FMO1) were downregulated in hepatotoxicity pathway, two genes (SREBF1 and FASN) in steatosis, one each in necrosis (IPO4) and phospholipidosis (SLC2A3) pathways." (PMID 38992651, 2024).
trimethylaminuria (1 paper, 2024). A rare inborn error of metabolism characterized by the presence of large amounts of trimethylamine in urine, sweat, and breath, resulting in a fishy body odor in affected individuals. "The duplicated regions harbor a total of five protein-coding genes: MROH9 and members of the flavin-containing monooxygenase family, including FMO3 (mutations cause the recessive disorder Trimethylaminuria; MIM 602079), FMO2, FMO1, and FMO4, all located within the chr1_D region." (PMID 39257002, 2024).
Type 2 diabetes (1 paper, 2011). "One gene, Fmo1, was inhibited in both Type 1 and Type 2 diabetes, and this inhibition was completely reversed in both conditions by the ketogenic diet." (PMID 21533091, 2011).
viral infection (1 paper, 2018). "Pip and its FMO1-dependent N-oxygenation product, N-hydroxypipecolic acid can play a critical role in the induction of SAR either after bacterial or viral infection in different host plants." (PMID 29642641, 2018).
infection (28 papers, 2013 to 2025). The state of being infected such as from the introduction of a foreign agent such as serum, vaccine, antigenic substance or organism. "Induction of FMO1 expression at the site of pathogen infection is attenuated by the recessive mutations in EDS1 and PAD4 genes." (PMID 32987853, 2020). "In Arabidopsis (Arabidopsis thaliana), the enzyme FLAVIN-DEPENDENT MONOOXYGENASE 1 (FMO1) catalyzes the N-hydroxylation of lysine-derived pipecolic acid (Pip) in response to pathogen infection to produce NHP." (PMID 39404105, 2024). "NRG and SAR proteins from the SA activating pathway and FMO1 from the pipecolic acid pathway are found to be down-regulated in resistant plants during infection, resulting in increased regulation of JA signaling and consequent defense responses." (PMID 37821523, 2023). "One example was an ortholog of the Arabidopsis FMO1 gene involved in biosynthesis of L-pipecolic acid, a long-distance signal of systemic acquired resistance (elevated 161-fold by infection in the GmPH lines, but only 73-fold in the VAM lines)." (PMID 35783378, 2022). "Defense gene induction by Pip is dependent on functional FMO1 (expression was elevated in C24 as early as 2 h post infection), suggesting the requirement of N-hydroxy-Pip formation and accumulation upon pathogen attack for SAR-related gene expression." (PMID 36292941, 2022). "Recently, N-hydroxypipecolic acid was found to be the product of FMO1 from Pip, and it can accumulate upon infection." (PMID 30544557, 2018). "FMO1 is a critical regulator of systemic acquired resistance to pathogen infection." (PMID 41196880, 2025). "Notably, fmo1 null mutants are impaired in local disease resistance during pathogen infection and fail to establish SAR." (PMID 39404105, 2024). "H2O2 levels in PeX collected from che and NHP-deficient ald1 and fmo1 mutants increased similarly to WT after infection, while no increase was detected in rbohD, demonstrating that H2O2 production in PeX requires RBOHD, but not NHP." (PMID 39265009, 2024). "Finally, the high susceptibility of the sid2 fmo1 and sid2 ald1 double mutants indicate that the SA and NHP signalling pathways act additively to basal immunity against infection by compatible bacterial pathogens." (PMID 37645466, 2023). "41,44 Our results verified that the absence of GI leads to downregulation of FMO1 after Hpa Noco2 infection, hence making the plant more susceptible than Col-0 plants." (PMID 35379074, 2022). "In addition to nontargeted metabolome analysis, we quantitatively analyzed the amount of NHP, NHP-OGlc, SA, and SAG in wild-type (Col-0), fmo1-1, and ugt76b1-1 plants after infection with P.s.m.." (PMID 33955489, 2021). "Additionally, we observed an about 2.5-fold higher accumulation of SA after infection in ugt76b1-1 plants compared to the wild-type, whereas fmo1-1 plants exhibited comparable SA levels to the wild-type, and moderately reduced SAG levels." (PMID 33955489, 2021). "However, the PR1 expression levels in the WT and pDEX::ALD1 line #6 were induced in distal tissue after primary infection alone and also after secondary infection, while FMO1 expression levels were induced only after secondary infections." (PMID 33463678, 2021). "The positive interplay between NHP and SA in plant immunity is also reflected in an increased susceptibility to infection by P. syringae of both NHP- and SA-deficient ald1 sid2 or fmo1 sid2 double mutants compared to the respective single mutants that only lack one of the two immune regulators." (PMID 33871649, 2021). "Although induction of the pathway after P. syringae inoculation was associated with further increases in the level of ALD1 transcripts, the de novo expression of FMO1 after pathogen infection appears to be the major pathogen-inducible trigger that switches on the generation of NHP." (PMID 32725118, 2020).
infection (continued). "In addition, FMO1 is not only necessary for systemic accumulation of SA and downstream signaling after pathogen infection but also regulates PCD in Arabidopsis." (PMID 31024626, 2019). "Interestingly, besides the inability of fmo1 to mediate Pip-induced resistance, fmo1 over-accumulates Pip in the pathogen-inoculated tissue during the later stages of infection." (PMID 23440336, 2013). "To test whether MeNHP is able to prime the defense response in Arabidopsis and further to rescue the fmo1-1 infection phenotype, we challenged MeNHP-treated fmo1-1 and Col-0 plants with a spore solution of H. arabidopsidis Noco 2 and analyzed spore growth on mock- or MeNHP-treated plants." (PMID 36260503, 2023). "Furthermore, it can restore the resistance against infection for the FMO1 mutant." (PMID 30544557, 2018). "Specifically, out of three enzymes involved in taurine synthesis, namely GAD, CSAD and FMO1, only FMO1 was found to have a substantial impact over CHIKV infection and oxidative stress during the infection." (PMID 37130109, 2023). "Further, Noco2 infections also lead to increased expression of PAD4 and its downstream defense signaling genes like ICS1, PR1, FMO1, and PBS3." (PMID 35379074, 2022). "When exogenously supplied to Arabidopsis, NHP potently activated SAR to bacterial (P. syringae) and oomycete (Hyaloperonospora arabidopsidis) infections and overrode the SAR incompetence of fmo1 mutant plants." (PMID 32725118, 2020). "Conversely, NAD is able to overcome this stressful condition by over-expressing ABA–related receptor genes such as FMO1, a gene expressed only in NAD in response to infection." (PMID 28367157, 2017). "To determine whether SA and NHP biosynthesis is required for antiviral SAR in the suppression of PlAMV-GFP infection in untreated distal leaves, we tested the Arabidopsis sid2-2 mutant, which lacks ICS1 function, and the NHP biosynthesis mutant fmo1." (PMID 38339085, 2024). "FMO1 is involved in the catalytic conversion of pipecolic acid to N-hydroxypipecolic acid (NHP), which plays a role in plant-acquired systemic resistance to infection by pathogens." (PMID 35089084, 2022). "In the SAR-deficient ald1 mutant, the PR1 expression levels were not altered by any infection, while the FMO1 level was not induced by immunization infection and showed no priming effect." (PMID 33463678, 2021). "The transcripts, however, were almost exclusively located in the pericarp (97%) samples, rather than peel, suggesting that if FMO1 plays a role in resistance to P. capsici, it likely occurs at an infection step post-penetration." (PMID 26528543, 2015). "In the course of infection, G. orontii manipulate WRKY18 and 40 transcription factor activities to modulate the expression of JAZ repressor genes and defense response genes, such as FMO1 and CYP71A13 to its advantage." (PMID 23516362, 2013). "Interestingly, the systemic expression of the FMO1 gene depends on phytochromes during SAR establishment, since phyAphyB double mutant did not increase the expression of FMO1 in systemic leaves upon pathogen infection." (PMID 32987853, 2020).
bacterial infection (2 papers, 2020 to 2023). "To directly assess basal immunity to bacterial infection, we inoculated leaves of naïve Col-0, sid2, ald1, fmo1, sid2 ald1, sid2 fmo1 and ald1 fmo1 plants with the compatible Psm or P. syringae pv." (PMID 37645466, 2023). "Upon bacterial infection, fmo1 mutant fails to form lesions and allows pathogen invasive growth, but introducing wild type FMO1 complements the fmo1 defects in pathogen resistance." (PMID 32987853, 2020).
cancer (2 papers, 2017 to 2023). A tumor composed of atypical neoplastic, often pleomorphic cells that invade other tissues. "The pan-cancer analysis in TCGA and GEO datasets showed that FMO1 was upregulated, while FMO2 and FMO4 were downregulated in GC." (PMID 37274237, 2023).
tumor (2 papers, 2017 to 2023). "We found that FMO1 and FMO2 expression was associated with three and nine types of tumor-infiltrating immune cells, respectively." (PMID 37274237, 2023).
psychiatric disorder (1 paper, 2020). A disorder characterized by behavioral and/or psychological abnormalities, often accompanied by physical symptoms. "Although the enrichment does not reach significance following multiple hypothesis testing comparison, it is worth noting that additional genes are implicated in psychiatric disorders (GABRE, GNRH1, FMO1, FLG, SELE, NQO2)." (PMID 33169669, 2020).
FMO1 also shares sentences with these, for which no sentence is quoted: atrial fibrillation (1 paper); cardiac hypertrophy (1); hepatoma (1); periodontitis (1).